VIM (vimentin)
Description:
Vimentins are class-III intermediate filaments found in various non-epithelial cells, especially mesenchymal cells. Vimentin is attached to the nucleus, endoplasmic reticulum, and mitochondria, either laterally or terminally. Plays a role in cell directional movement, orientation, cell sheet organization and Golgi complex polarization at the cell migration front (By similarity). Protects SCRIB from proteasomal degradation and facilitates its localization to intermediate filaments in a cell contact-mediated manner (By similarity). May promote axon outgrowth and motor fiber repair via DSP-mediated recruitment to outgrowth tips (By similarity). Involved with LARP6 in the stabilization of type I collagen mRNAs for CO1A1 and CO1A2.
Tractability: Small molecule: it has a high-quality binding pocket. Antibody: a drug acting on it is in phase 2 or 3 trials; UniProt places it where antibodies can reach, with medium confidence; its Gene Ontology location is reachable by antibodies, with medium confidence. PROTAC: UniProt records ubiquitination sites on it; ubiquitination databases record sites on it; its protein half-life has been measured.
Target class: Structural protein
Gene: Protein-coding gene on chromosome 10 (17,228,241 to 17,237,593, forward strand). Ensembl gene ENSG00000026025.
Subcellular location: Cytoplasm; Cytoplasm, cytoskeleton; Nucleus matrix; Cell membrane; Cell projection, axon
Subcellular location (Human Protein Atlas): Intermediate filaments
Pathways (Reactome):
Autophagy: Aggrephagy; Chaperone Mediated Autophagy; Late endosomal microautophagy
Disease: Dengue Virus Genome Translation and Replication; Dengue Virus-Host Interactions
Developmental Biology: Developmental Lineage of Mammary Gland Myoepithelial Cells
Immune System: Interleukin-4 and Interleukin-13 signaling
Muscle contraction: Striated Muscle Contraction
Programmed Cell Death: Caspase-mediated cleavage of cytoskeletal proteins
Signal Transduction: RHOBTB1 GTPase cycle
Gene Ontology:
Molecular function: double-stranded RNA binding; identical protein binding; keratin filament binding; molecular adaptor activity; protein binding; protein domain specific binding; scaffold protein binding; structural constituent of cytoskeleton; RNA binding; structural constituent of eye lens
Biological process: cellular response to lipopolysaccharide; cellular response to muramyl dipeptide; positive regulation of collagen biosynthetic process; regulation of mRNA stability; intermediate filament organization; positive regulation of axon extension; positive regulation of protein localization; positive regulation of gene expression
Cellular component: cytoplasm; cytoskeleton; cytosol; extracellular exosome; focal adhesion; intermediate filament; intermediate filament cytoskeleton; peroxisome; axon; microtubule organizing center; nuclear matrix; plasma membrane; cell leading edge; neuron projection; phagocytic vesicle
Genetic constraint (gnomAD): Loss-of-function variants: 18 observed, 49.28 expected, observed/expected ratio (o/e) 0.37, 90% interval 0.25 to 0.54. The upper end of that interval is the gene's LOEUF score, 0.54, which puts it in group 2 of 6, group 1 being the genes least tolerant of losing a copy. Missense variants: 551 observed, 608.82 expected, observed/expected ratio (o/e) 0.91, 90% interval 0.84 to 0.97. Synonymous variants: 245 observed, 240.06 expected, observed/expected ratio (o/e) 1.02, 90% interval 0.92 to 1.13.
Homologues: Orthologues: chimpanzee VIM (100% identical), macaque VIM (99% identical), rat Vim (98% identical), mouse Vim (97% identical), rabbit VIM (97% identical), pig VIM (93% identical), guinea pig VIM (87% identical), tropical clawed frog vim (76% identical), zebrafish vim (68% identical), zebrafish viml (66% identical). Paralogues in human: DES (61% identical), PRPH (57% identical), GFAP (53% identical), INA (46% identical), NEFL (42% identical), NEFM (42% identical), KRT8 (34% identical), KRT84 (32% identical), KRT75 (32% identical), KRT1 (32% identical), KRT6C (31% identical), KRT73 (31% identical), and 56 more.
Diseases named in the same sentence as VIM in open-access papers:
VIM is named in the same sentence as 781 diseases in open-access papers, as found by Europe PMC text mining. Sharing a sentence is not in itself a finding about the gene and the disease. The quoted sentences say what the papers report.
breast carcinoma (953 papers, 1995 to 2026). "Among the plethora of factors implicated in the progression of breast cancer, vimentin (VIM) has been identified as a pivotal element." (PMID 39781570, 2025). "This also strongly suggests that vimentin is closely associated with more aggressive forms of breast cancer." (PMID 39858010, 2025). "This reduction in Wnt signaling is associated with decreased EMT by suppressing vimentin and snail expression in endocrine-resistant breast cancers." (PMID 40569965, 2025). "In this context, it was observed that the rather weak expression of vimentin, a mesenchymal marker associated with poor prognosis in breast cancer, was markedly stimulated by co-culturing EM-G3 cells with fibroblasts." (PMID 37975220, 2024). "NF-κB increases EMT-associated genes SNAI1, TWIST1, ZEB1, and VIM in a variety of disease processes including pulmonary lung fibrosis and many cancers: head and neck, prostate, pancreatic, and breast cancer." (PMID 39348939, 2024). "Vimentin is associated with poor prognoses and invasion of breast cancer, bladder cancer, esophageal cancer, lung cancer, and other cancers, and it is a potential target for cancer treatment." (PMID 36631457, 2023). "Overexpression of RPLP1 in MDA-MB-231 breast cancer cells was associated with significant increases in protein expression for N-cadherin, snail and vimentin." (PMID 36769010, 2023). "It has been reported that STAT3-mediated breast cancer cell metastasis is associated with the upregulation of vimentin, MMP-2, and MMP-9." (PMID 37836626, 2023). "Vimentin is another mesenchymal marker for EMT, and several reports have demonstrated that vimentin is overexpressed in cancers, such as gastric cancer, breast cancer, and prostate cancer, which is associated with invasive phenotype and poor prognosis." (PMID 36866240, 2023). "This is consistent with reports from others that miR-21-deficient breast cancer cells exhibited a diminished N-cadherin, snail, and vimentin expression profile, supporting the notion that miR-21 plays a mechanistic role in EMT progression." (PMID 36765584, 2023). "Studies in Src-inhibited breast cancer cells revealed an increase in E-cadherin with an associated decrease in vimentin, a transition to a prior epithelial phenotype, and a blockade of cancer cell migration." (PMID 36547158, 2022). "Vimentin is overexpressed in many epithelial carcinomas, such as prostate cancer, lung cancer, breast cancer, and gastric cancer, and is associated with tumor invasion and poor prognosis." (PMID 35320951, 2022). "Vimentin has been extensively investigated in breast cancer where its expression is a hallmark of EMT." (PMID 36362433, 2022). "Overexpression of CPEB4 is associated with tumor growth, vascularization, migration, invasion and metastasis in breast cancer patients, causing an upregulation of Vimentin expression and promoting EMT, invasion and migration of breast cancer cells." (PMID 36052258, 2022). "In good agreement with our findings, a study that investigated the expression of some EMT markers during breast cancer progression also demonstrated vimentin expression positivity associated with aggressive tumors such as the triple-negative subtype." (PMID 34827233, 2021). "In a number of triple-negative breast cancers, vimentin expression has been identified as a marker of basal-like breast cancer cells associated with poor prognosis." (PMID 34577566, 2021). "It has been reported that the upregulation of ID2 in breast cancer is associated with a reduced vimentin expression and attenuated EMT features in triple-negative breast carcinomas." (PMID 35008299, 2021). "To clarify which kind of cells are responsible for the deficiency of HA cross-linking in breast cancer, we simultaneously determined the expression of HA and vimentin using immunofluorescence." (PMID 34099638, 2021).
breast carcinoma (continued). "Since in MDA-MB-231 breast cancer cells, the vimentin depletion has been associated with reduced proliferation and affected wound healing, it can be said that the 48 h treatment with EE-LNG positively impacted the invasiveness of the cells." (PMID 34066763, 2021). "The expression of ETS-1 mRNA is related to the EMT phenotype, which is characterized by vimentin expression and E-cadherin deficiency in breast cancer cell lines." (PMID 32799885, 2020). "The finding prompted us to compare the expression patterns of SIPA1 with two molecules, vimentin and E-cadherin, which are closely associated with epithelial and mesenchymal features, in TCGA breast cancer patient samples." (PMID 32193333, 2020). "Epithelial‐mesenchymal transition is a well‐recognized process underlying breast cancer cell metastasis, and E‐cadherin and vimentin are important EMT markers." (PMID 31273950, 2019). "Taken together, these results suggest that RNF208 expression is closely associated with Vimentin-mediated aggressive cancer progression of breast cancer cells." (PMID 31862882, 2019). "It has been demonstrated that vimentin is necessary for wound healing both in cultured cells and in animal models and is associated with invasive behavior in prostate and breast cancer." (PMID 31073526, 2019). "Fibroblasts from vimentin-deficient mouse exhibited a reduction in cell motility, defects in directionality and on their ability to organise collagen, while vimentin overexpression caused increased cell motility of breast cancer cells." (PMID 31569795, 2019). "EMT-associated markers EGFR, EpCAM, fibronectin and vimentin were also evaluated using immunofluorescence for the six breast cancer cell lines." (PMID 31430931, 2019). "β-Catenin is a marker of poor prognosis in human cancer and has been implicated in human breast cancer, via targeting cyclin D1 or vimentin." (PMID 30181805, 2018). "Vimentin-associated migration in pre-malignant breast cancer cells has been shown to be induced by H-Ras-V12G and Slug." (PMID 30248895, 2018). "Vimentin overexpression has been found in several cancer cells, including breast cancer, and this overexpression has been associated to an increase in cell invasion and tumor growth." (PMID 30123423, 2018). "Consistent with that report, we also confirmed that lncATB promoted the EMT by inducing the expression of mesenchymal hallmarks, such as N-Cad and Vimentin, and inhibiting the expression of the epithelial hallmark E-Cad in breast cancer cell lines." (PMID 30518916, 2018). "FBXO4 overexpression decreased EMT in metastatic breast cancer cells with a loss of fibronectin, vimentin, and ZEB1." (PMID 29137327, 2017). "Immunofluorescence staining performed in our experiments showed that about 90% of breast cancer cells had lost the expression of Vimentin concomitantly with a loss of their mesenchymal phenotype after exposure to hESCs-CM." (PMID 28068409, 2017). "Linear regression analysis showed a positive correlation between p62 and vimentin protein expression (R2 = 0.7539, P = 0.0011), indicating that p62 overexpression is associated with high vimentin levels in clinical breast cancer tissues." (PMID 28968743, 2017). "Silencing ROR1 expression by siRNA reduces the expression of EMT-associated proteins, such as SNAIL-1/2, ZEB1, CXCR4, and vimentin in breast cancer cell line MDA-MB-231." (PMID 27830754, 2016). "EMT is significantly associated with these types of breast carcinoma, particularly with increased expression of mesenchymal cytoskeletal proteins such as vimentin." (PMID 27829223, 2016). "For the MCF10A to MDA-MB-231 comparison, MSigDB gene expression datasets defining breast cancer cell subtypes were used to select well-established EMT associated genes (VIM, CDH1, ZEB1) as central nodes to define an IPA gene association network." (PMID 26783963, 2016).
breast carcinoma (continued). "For instance, methylation of the VIM gene encoding the EMT indicator vimentin is associated with a markedly decreased survival in breast cancer." (PMID 26506390, 2015). "Vimentin is associated with cancer invasion and poor prognosis in numerous types of cancers, including breast cancer, prostate cancer, melanoma, and lung cancer, and serves as a potential target for cancer therapy." (PMID 25965826, 2015). "Vimentin expression is associated with the upregulation of N-cadherin, and a previous study has demonstrated that the overexpression of vimentin in breast cancer is related to a poor prognosis." (PMID 25909322, 2015). "Forced expression of miR-200c restores the chemotherapeutic sensitivity of breast cancer cells, while loss of miR-200 correlates with increased vimentin expression and decreased E-cadherin expression in breast cancer cells." (PMID 25944619, 2015). "Others and we have shown that 50–75% of TNBC breast cancers express vimentin, which is associated with high tumor grade, ER−/PR− status, and chemo-resistance." (PMID 25749031, 2015). "Further, it was reported that loss of cytokeratin and gain of vimentin expression are indicators of biologically aggressive breast carcinoma." (PMID 25268751, 2014). "The intriguing finding concerning the efficacy of taxanes can be explained by investigating the expression of Vimentin, a protein that has been linked to taxanes resistance in breast cancer and considered a marker for adverse prognosis." (PMID 24632568, 2014). "Other reports have suggested that the elevation of K18 expression in breast cancer patients correlates with favourable prognosis and that the loss of K8 in conjunction with aberrant expression of vimentin correlates with early metastasis and poor prognosis." (PMID 23341946, 2013). "Breast cancer cells become more aggressive and malignant with the loss of keratin as these proteins are replaced with vimentin, the intermediate filaments-protein of mesenchymal cells." (PMID 24034496, 2013). "Inhibition of P2X5 reduces expression of the EMT marker vimentin and its increased expression correlates with breast cancer cells that are associated with a more mesenchymal phenotype." (PMID 21850275, 2011). "EMT has recently been linked to basal-like breast cancer as demonstrated by upregulation of EMT markers (Vimentin, alpha-smooth muscle actin, and N-Cad) together with reduction of characteristic epithelial markers (E-Cad and keratins)." (PMID 21915264, 2011). "Numerous studies relating to proteomics have shown that vimentin was metastasis-associated factor in multiple malignancies, such as prostate cancer, breast cancer, gastric cancer, and galbladder cancer." (PMID 20701774, 2010). "Several cell lines were further classified as representing breast cancers that had undergone an epithelial-to-mesenchymal transition based on their expression of vimentin and the loss of cytokeratin expression." (PMID 19874578, 2009). "Co-expression of VIM and cytokeratins (CKs) is associated with a more aggressive and metastatic phenotype in breast cancer; however our data demonstrates increased expression of VIM with an associated decrease in cytokeratin 18 levels in Clone #3." (PMID 19216797, 2009). "In addition, FBXO24-mediated depletion of LSD1 level reduced breast cancer cell migration and invasion, which was associated with the increased expression of E-cadherin and reduced expression of Vimentin." (PMID 40940894, 2025). "Additionally, Ep-CAMhi expression significantly correlated with breast cancer cases exhibiting combined vimentin overexpression and loss of E-cadherin (p = 0.045), a strong feature of EMT." (PMID 40943144, 2025). "In breast cancer, Datar and Schalper showed that increased vimentin/reduced E-cadherin is associated with PD-L1 upregulation and escape of the tumor from the immune system, while downregulation of PD-L1 correlates with low expression of mesenchymal phenotype in breast cancer." (PMID 38398019, 2024).
breast carcinoma (continued). "Although high expression of vimentin is associated with poor recurrence-free survival of breast cancer patients, it is unclear whether simultaneous high expression of both vimentin and plectin leads to a worse scenario." (PMID 39542246, 2024). "Mangiferin, present in mango, inhibits cell proliferation and metastatic ability in breast cancer cells by inhibiting the activation of the β-catenin pathway, lowering the expression of matrix metalloproteinase-7, -9, and vimentin, and causing the reversal of the epithelial-mesenchymal transition." (PMID 37169856, 2023). "Therefore, a high level of vimentin expression has been associated with increased risks of metastasis and represents poor prognosis in a variety of cancers, including breast cancer, prostate cancer, melanoma, and lung cancer." (PMID 36631457, 2023). "Moreover, the upregulation of FN1, CDH2, and VIM is commonly associated with the epithelial–mesenchymal transition (EMT) in breast cancer and also in mammary epithelial cells." (PMID 36013233, 2022). "Moreover, the focal adhesion scaffold protein Hic-5 has been implicated in the regulation of vimentin networks in fibroblasts, as well as cell shape and invasion of breast cancer cells." (PMID 33691719, 2021). "To test this, we compared the expression of mRNAs encoding CD73 with E-cadherin and vimentin expression in 1904 breast cancer specimens from the METABRIC study (Molecular Taxonomy of Breast Cancer International Consortium) database available in cBioPortal29–31." (PMID 33727591, 2021). "Importantly, our data show a strong association between vimentin and PD–L1 as previously reported in human esophageal and breast cancers." (PMID 31546725, 2019). "The apoptotic and antiangiogenic properties of withaferin-A were shown to be significantly reduced in vimentin-deficient cells, and withaferin-A treatments have been shown to be beneficial in vivo for patients with breast cancer, cervical cancer, and pancreatic cancer." (PMID 30248895, 2018). "It is therefore possible that transcriptional induction of PPFIA1 by Snail1 may contribute to the invasive phenotype of breast cancer cells and the induction of vimentin intermediate filament assembly, a hallmark of EMT." (PMID 29729076, 2018). "Similarly, metformin has been shown to impede TGF-β-promoted loss of the epithelial marker E-cadherin in MCF-7 breast cancer cells, and to prevent accumulation of the mesenchymal marker vimentin in Madin-Darby canine kidney cells." (PMID 28147330, 2017). "It is known that the vimentin promoter is a direct target of β-catenin/TCF transactivation in breast cancer cells and the cytoplasmic and nuclear localization of β-catenin in mammary human epithelial cell lines is associated with vimentin expression leading to high invasive/migratory potential." (PMID 25268751, 2014). "Thus, we can suggest an improved indicator of breast cancer progression by adding vimentin to the diagnostic panel when overall survival is a primary end-point." (PMID 24527079, 2014). "Importantly, loss of p21 is correlated with positive vimentin expression in primary human breast cancers." (PMID 23805223, 2013). "Since TGF-β has been implicated in regulation of vimentin and promoting cell migration, we studied whether stimulation of metastatic breast cancer cells with TGF-β affects MTHFD2 expression." (PMID 23295955, 2013). "Vimentin expression in breast carcinomas may have an association with poor prognosis, hormone receptor negativity and co-expression of EGFR, which are consistent features for basal-like tumors." (PMID 23082819, 2012). "Moreover, the simultaneous expression of vimentin and cytokeratin in tumour cells is associated with poorer survival in breast cancer patients." (PMID 21663619, 2011). "However, we cannot offer a better indicator of basal type breast cancers by adding vimentin to the diagnostic panel when overall survival is a primary end-point." (PMID 19695088, 2009).